BRCA2 (BRCA2 DNA repair associated)
Diseases named in the same sentence as BRCA2 in open-access papers (continued):
Sharing a sentence is not in itself a finding about the gene and the disease.
tumor (continued). "The evidence that PALB2 is critical for HR and functions as a breast and pancreatic susceptibility gene suggest that the role of the adaptor protein, PALB2, may be critical for BRCA1/2- mediated tumor suppression by physically linking BRCA1 to BRCA2." (PMID 31877165, 2019). "However, we found that age at diagnosis, laterality (in BRCA2 carriers), tumor stage and presence of multiple neoplasms were significantly associated with BRCA mutations." (PMID 31771539, 2019). "The human BRCA2 gene is a tumor suppressor which contains 27 exons and spans about 70 kb." (PMID 30940775, 2019). "A recent study showed that SOX2 overexpression was found in a proportion of women with BRCA1 and BRCA2 mutations who underwent prophylactic salpingo-oophorectomy, and in the majority of patients with HGSOCs, irrespective of tumor stage." (PMID 31850198, 2019). "Molecular testing determined that his t-NEPC tumor (but not his original adenocarcinoma) harbored complete copy number loss of BRCA2, as well as copy number loss of another HR gene - ataxia telangiectasia, mutated (ATM)." (PMID 31565603, 2019). "BRCAnesswas described as a phenomenon in which HR deficiency occurs in a tumor not dueto a BRCA1 or BRCA2 germline mutation, but bymutations in other genes involved in HR." (PMID 31067289, 2019). "The rate of BRCA1/BRCA2 mutation detection in those studies, selected based on the tumor triple negativity, independent of family history, varies from 17.4% to 49.1%." (PMID 31244284, 2019). "Treatment with each of the three drugs showed tumour growth inhibition at the nadir of the effect of 89, 89 and 85%, respectively, with a progression‐free survival of 19, 21 and 24 days, suggesting similar anti‐tumoral activities against BRCA2‐defective tumours." (PMID 31273933, 2019). "In fact, TNBC represents the predominant tumor type in patients with BRCA1 mutations, accounting for 71% (range 42-100%) of tumors, while TNBC has been diagnosed in only 25% of patients with germline BRCA2 mutations." (PMID 31379942, 2019). "Now, new roles for BRCA1 and BRCA2 are emerging and old concepts,such as the classical two-hit hypothesis for tumor suppression, have beenquestioned, at least for some BRCA functions." (PMID 31067289, 2019). "Since BRCA1/BRCA2 mutations have not been found in RMS tumours, the presence of genetic/epigenetic alterations in other DNA repair machinery components or related factors cannot be excluded." (PMID 30357520, 2019). "find that the BRCA2 tumor suppressor controls transcription elongation by RNA polymerase II." (PMID 29386125, 2018). "Inevitably, there have been substantial changes in the management of BRCA1 and BRCA2 mutation carriers since the recruitment period of this study, including the exploration in trials of systemic therapies that exploit BRCA-null tumours, including platinum-based drugs and PARP inhibitors." (PMID 29337092, 2018). "We have demonstrated that compared to primary chemoresistant HGSOC, LT survival in HGSOC can be characterized by elevated mutation burden, biallelic inactivation of BRCA1 or BRCA2, and increased CD4+ and CD8+ lymphocytic infiltration in the tumor microenvironment." (PMID 30382883, 2018). "Of note, tetraploidy was also reported in BRCA2-associated tumours associated with the luminal molecular subtype and loss of the normal allele, although this result was not confirmed when BRCA2 CNV profiles were investigated with SNP array and GAP methods." (PMID 29665859, 2018).
tumor (continued). "A consensus panel of such molecular alterations could serve as biomarker for monitoring the risk of developing neoplastic disease in these patients as do BRCA1, BRCA2 and ER/PR/HER2 biomarkers for BCa25–27,52." (PMID 30054559, 2018). "BRCA2 is a tumor suppressor gene that mediates the repair of chromosomal damage." (PMID 30186165, 2018). "In the BT20 model which bears a BRCA2 mutation, Rucaparib treatment decreased tumor growth as expected, but HORMAD1 overexpression did not affect baseline tumor growth or response to Rucaparib." (PMID 30046392, 2018). "BRCA2 is a tumor suppressor that prevent cells from growing and dividing too rapidly." (PMID 30001383, 2018). "Brca2-deficient BRE overexpressing cells (KB2P1.21 + BRE) showed accelerated tumor growth relative to cells without BRE overexpression." (PMID 29416040, 2018). "Of these twoone had shallow loss of BRCA2 with no alteration detected in the other allele, and one had no tumor tissue available for analysis." (PMID 30514390, 2018). "Cluster A tumours showed an earlier age at diagnosis than other BRCA2 tumours." (PMID 28893223, 2017). "Our discovery that MUS81 inactivation is lethal when combined with BRCA2 deficiency identifies MUS81 as a potential target for the development of drugs that could selectively eliminate BRCA2-compromised cells and tumours." (PMID 28714477, 2017). "An alternative explanation is that BRCAness exists when a DDR defect is present in a tumour in the absence of a germline BRCA1 or BRCA2 mutation." (PMID 29069866, 2017). "Based on the genetic heterogeneity of the observed mutation spectrum, sequencing of the entire open‐reading frame (ORF) of BRCA1 and BRCA2 using tumor‐derived DNA is required to identify the patients who may benefit from this treatment." (PMID 27767231, 2017). "To gain mechanistic insight into USP21 function in HCC, we asked whether USP21 can modulate BRCA2 stability in HCC-derived tumor cells." (PMID 28743957, 2017). "Similarly, BRCA2-mutant tumours showed elevated numbers of SNVs and GRs than sporadic tumours arising in either older or younger men." (PMID 28067867, 2017). "BRAC1 and BRCA2 are two classic tumor suppressor genes which play an important role in DNA repair." (PMID 28415599, 2017). "Finally, we provide evidence that, albeit priming fork degradation, reversal of stalled forks is essential to prevent excessive chromosomal breakage in BRCA2-defective tumor cells." (PMID 29038466, 2017). "Notably, in our cohort a high AMI maintained a trend towards prognostic significance in BRCA2 tumours further suggesting that as above, methylation has particular biological importance in this subset of tumours." (PMID 28893223, 2017). "Application of this model allowed the identification of additional tumours with alteration of BRCA1 or BRCA2, which could have selective therapeutic sensitivity to PARP inhibition." (PMID 28491135, 2017). "BRCA2-mutant PCa tumours showed similar chromothriptic character to sporadic disease." (PMID 28067867, 2017). "In the PEO1 cell line established from the tumour before the emergence of cisplatin resistance, cisplatin selection led to TAG > TTG mutations of the stop codon in eight out of eight resistant clones that restored the BRCA2 protein." (PMID 27161042, 2016). "All patients with germline mutations in BRCA1 (but none of the BRCA2-carriers) were predicted to carry a tumor with a basal-like subtype and the variants were all listed as known pathogenic in ClinVar36." (PMID 27901097, 2016). "To assess whether the increased sensitivity of BRCA2-deficient cells towards TRAIL-R-targeting compounds observed in vitro was transferable to the in vivo setting, we applied a murine tumor xenograft model." (PMID 26843614, 2016). "Similarly, DNA methylation at 10 CpG probes across the BRCA2 promoter region was increased in the tumor-derived DNA compared with blood-derived DNA (Δβ 5.49%; adj." (PMID 27902704, 2016).
tumor (continued). "To test this hypothesis, we used three human tumor cell lines with varying degrees of HRR proficiency: SKOV-3 (BRCA2 WT), MCF-7 (HRR deficient), and CAPAN-1 (BRCA2 mutant)." (PMID 26959114, 2016). "Here they define BRCAness as “a situation in which an HR defect exists in a tumor in the absence of a germline BRCA1 or BRCA2 mutation”." (PMID 27756336, 2016). "These types of tumours are associated with BRCA1 and BRCA2 mutations." (PMID 27884978, 2016). "BRCA2 is a tumour suppressor gene identified as a factor for heritable cancer susceptibility." (PMID 27689078, 2016). "The abundant ssDNA-binding protein, replication protein A, transiently engages the single-stranded 3′ tail, but is replaced by RAD51, whose nucleation on ssDNA is stabilized by the evolutionarily conserved BRC repeat motifs within the BRCA2 tumour suppressor protein." (PMID 27596592, 2016). "BRCA1 gene located on chromosome 17q21 and BRCA2 gene located on chromosome 13q12 are tumor suppressor genes involved in maintaining of genome integrity by engaging in many processes such as repair of DNA double strand breaks, cell cycle control and transcription." (PMID 27129401, 2016). "An important functional consequence of fork protection associated with PTIP loss is resistance to PARPi and cisplatin in Brca2-deficient tumour cells that is independent of the presence of secondary reversion mutations." (PMID 27498558, 2016). "On the other hand, we observed that the African ancestry component among individuals without BRCA1/BRCA2 mutations was associated with higher tumor grade (p = 0.008)." (PMID 27741520, 2016). "The data from our mixed cell experiments suggests that simultaneous inhibition of BRCA2 and olaparib treatment has the ability to limit the proliferation of tumor cells heterogeneous for HRR-proficiency, thus preventing positive selection of resistant cells based on ability to repair DNA." (PMID 26959114, 2016). "One BRCA2 variant was not classifiable because DNA from non-tumor control tissues was not available." (PMID 27907908, 2016). "More intriguingly, RAD52 depletion is also synthetically lethal with defects in BRCA1, a tumor suppressor that acts upstream of BRCA2 in HR and at the branch point in the DSB repair that promotes homology-directed DNA repair through HR or SSA over the NHEJ (non-homologous end joining)." (PMID 27434671, 2016). "However, further experiments are necessary to determine the effect of BRCA2 inhibition and olaparib treatment on survival of tumor-bearing animals." (PMID 26959114, 2016). "We further investigated possible reasons why canine BRCA2 expression was reduced in tumor samples: mutations in the BRCA2 promoter region and non-sense mRNA decay (NMD) induced by PTCs that can form in splice variants." (PMID 26202431, 2015). "Also, in hematopoietic progenitors from DBA patients, some members of the RAS family are upregulated, whereas the tumor suppressors breast cancer 2, early onset (BRCA2) and retinoblastoma 1 (RB1) are downregulated." (PMID 26398160, 2015). "In other words, the reduced BRCA2 expression leads to tumor formation." (PMID 26202431, 2015). "One possible reason for reduced BRCA2 mRNA levels in these tumor samples was nonsense-mediated mRNA decay, not mutations in the BRCA2 promoter region." (PMID 26202431, 2015). "Subsequent work has shown that, in addition to BRCA1/BRCA2 mutations, BRCA-like tumours may also have implications for PARPi-based therapy." (PMID 26610585, 2015). "BRCA2 and the Rad51 paralogs are tumor suppressors and critical mediators of Rad51." (PMID 26186187, 2015).
tumor (continued). "Our results indicated that germline truncation and missense variants in several genes were under selection in the tumour, with ATM, BRCA1, BRCA2 and RAD51C determined as significant from both truncation and missense analyses and BAP1, BRIP1, FANCM, PALB2 and RAD51D from truncation analysis alone." (PMID 26689913, 2015). "Tumor and genomic DNA from patients with BRCA1 promoter methylation were screened for the three key founder mutations in the Ashkenazi Jewish population: BRCA1 185delAG, 5382insC, and BRCA2 6174delT." (PMID 25136623, 2014). "BRCA2 has been believed to follow the classical ‘two‐hit’ paradigm for tumour suppression." (PMID 24268522, 2014). "Data were available on tumor characteristics for 2,570 (59%) of the 4,330 affected BRCA2 carriers." (PMID 25919761, 2014). "Influential TFs identified in pancreatic (normal vs PDAC) and breast (BRCA1 vs BRCA2) tumours." (PMID 25521701, 2014). "Functional studies indicate that this protein may be an important cofactor for BRCA2 in tumor suppression and a modulator of CDK2 kinase activity via p21." (PMID 25330516, 2014). "Many of the PARPi currently under evaluation have been shown previously to have preferential cytotoxic activity for tumor cells with mutated or non-functional BRCA1 or BRCA2." (PMID 24970803, 2014). "Concurrent downregulation of IDO and BRCA2 sensitized tumor cells to olaparib (1 microM) to a greater degree than after knockdown of either target alone, possibly by reducing the capacity of these cells to repair DNA lesions result of their genomic instability." (PMID 24784564, 2014). "For example PARP inhibitors were demonstrated to be synthetic lethal in vitro with mutations in the tumor suppressors BRCA1 and BRCA2 and clinical testing has established the same genetic dependence on tumor sensitivity to the PARP inhibitor olaparib in patients." (PMID 25520658, 2014). "A subclass of tumours in C showed copy-number alterations in cell cycle regulation and DDR pathways attributable to amplification of the gene encoding the mitotic regulator AURKA kinase and the inactivation of BRCA1 and BRCA2 genes." (PMID 24792170, 2014). "We noticed over-expression of this complex in BRCA1 compared to BRCA2 tumours." (PMID 25521701, 2014). "The genomic findings of this study emphasize that BRCA2 tumours may be a distinct subgroup in familial MBC and as such BRCA2 mutation may be a significant driver in MBC." (PMID 23971979, 2013). "We tested 16 of the tumor specimens to determine whether they contained the common Ashkenazi Jewish founder mutations in BRCA1 (185delAG, 5382insC), and BRCA2 (6174delT)." (PMID 23855721, 2013). "One tumour arising in a BRCA1 carrier had an exon 20 PIK3CA mutation, five PIK3CA mutations occurred in BRCAX males whereas no PIK3CA mutation were identified in tumours from BRCA2 mutation carriers." (PMID 23971979, 2013). "To assess the impact of BRCA1 germline mutations on protein localization, we retrospectively tested 16 of the tumor specimens to determine whether they contained the common Ashkenazi Jewish founder mutations in BRCA1 (185delAG, 5382insC), and BRCA2 (6174delT)." (PMID 23855721, 2013). "Our preliminary results suggest low tumor Nmut may identify BRCA-associated primary tumors in which the original deficiency of BRCA1 and BRCA2 pathways, including impaired DNA repair, is compensated for by alternative pathways." (PMID 24265793, 2013).
tumor (continued). "It has been suggested that HDR is the major tumor suppressor function for both BRCA1 and BRCA2, since a deficiency in HDR leads to increased levels of NHEJ and single-strand annealing (SSA), both of which are error-prone processes that lead to genomic instability." (PMID 23802008, 2013). "Targeted sequencing of further MBC, and in particular non-BRCA2 tumours, may help determine a more accurate incidence and potential relevance of this uncommon mutation." (PMID 23971979, 2013). "Certainly, it might be speculated that BRCA1 and BRCA2 are important for tumor suppression by virtue of their function in HRR." (PMID 23675572, 2013). "Therefore, the effect of tumor Nmut on treatment response and outcome was chiefly confined to those tumors with either germline or somatic mutations in BRCA1 or BRCA2." (PMID 24265793, 2013). "We also report a relatively higher proportion of tumours with invasive micropapillary areas particularly within BRCA2-associated tumours, an association not previously reported." (PMID 23146383, 2012). "In addition, there is evidence for a deletion/translocation phenotype potentially linked to germline BRCA1/2 mutations, with a high prevalence of small deletions being particularly marked in BRCA2 null tumours." (PMID 22514011, 2012). "A substantial body of work indicates that tumours arising in patients with germline BRCA1 mutations are morphologically and genetically distinct from those arising in carriers of BRCA2 mutations and from tumours in patients lacking mutations." (PMID 22053997, 2011). "It is currently unclear whether these polymorphisms are associated with different tumour characteristics within BRCA1 and BRCA2 mutation carriers." (PMID 22053997, 2011). "More recently, it has been recognised that BRCA1 or BRCA2 mutant tumours are sensitive to PARP inhibitors and thus rapid and inexpensive BRCA1 and BRCA2 testing may be of direct clinical utility." (PMID 21702907, 2011). "In this respect, the network of genetic changes affecting 6q22.32-q22.33, 11q14.2-q24.1, and 17q24.1 identified in association with BRCA2wt loss could be of critical importance in promoting survival of BRCA2-defective tumor cells." (PMID 21958427, 2011). "As ZAR2 over expression decreased the levels of BRCA2 in the cells, this gene, if disregulated, and over expressed in the cells, it may promote the growth of the tumor." (PMID 20202217, 2010).